INS (insulin)
Diseases named in the same sentence as INS in open-access papers (continued):
Sharing a sentence is not in itself a finding about the gene and the disease.
Insulin resistance (continued). "Beyond a large number of cytokines which have been shown to be involved as mediators in cellular insulin resistance and beta-cell failure often under inflammatory conditions, other cytokines are reported to exert beneficial effects with regard to improved glucose tolerance and insulin sensitivity." (PMID 25025664, 2014). "Insulin treatment could reduce its expression only in vehicle treated cells (0.75 fold, P < 0.01) but not in palmitate treated cells thus demonstrating progression of insulin resistance." (PMID 24892004, 2014). "Moreover, gefitinib treatment in high-fat diet Mig-6d/d mice showed decreases in fasting insulin concentration and insulin resistance, suggesting gefitinib may improve metabolic syndrome in those with dysregulated EGFR and/or its signaling pathway." (PMID 25486251, 2014). "Moreover, PT sodium transport seems to be enhanced in insulin resistant humans, suggesting that the stimulatory effect of insulin on PT transport may be preserved in common forms of insulin resistance." (PMID 24982885, 2014). "Additionally fasting intact pro insulin could be used as a specific predictor of insulin resistance in type 2 diabetes." (PMID 26413493, 2014). "However, metformin-treated mice showed a significant decrease in the severity of HFD-induced insulin resistance and glucose intolerance, which were indicated by changes in plasma levels of glucose in response to a peritoneal injection of insulin and glucose, respectively." (PMID 24638078, 2014). "Defect in mitochondrial oxidative phosphorylation have been linked to insulin resistance, and there is also evidence suggesting that polymorphisms in PPARGC1A are associated with an increased relative risk of type 2 diabetes, defects in insulin secretion, and lipid oxidation." (PMID 25302081, 2014). "A recent study showed that in diabetic rats with insulin resistance and secretion deficit, long-term consumption of caffeine improved both sensitivity and glucose-stimulated insulin secretion, regardless of caffeine associated CHO addition; whereas, sucrose itself aggravated insulin resistance." (PMID 25100892, 2014). "However, when we adjusted for insulin resistance, thigh muscle retained beneficial associations with HbA1c and CHD—though there may have been residual confounding as calculated measures of insulin resistance are imprecise." (PMID 24862429, 2014). "Though the exact cause of SVI can not be ascertained from the present study, insulin resistance could be a plausible mechanism as fasting blood glucose, plasma insulin and HOMA-IR were significantly high in study group." (PMID 24265679, 2013). "Furthermore, it has been demonstrated that mice transfected with extra copies of the insulin gene produce elevated insulin levels, and they show insulin resistance, hyperglycemia, and hypertriglyceridemia, suggesting that insulin itself is an important contributor to insulin resistance." (PMID 23360495, 2013). "Thus, insulin resistance within AgRP neurons could remove a major inhibitory signal to these neurons ultimately contributing to impaired hepatic insulin sensitivity." (PMID 23550218, 2013). "Additionally, insulin has been shown to down regulate angiopoietin-like 4 in adipocytes and this down-regulation could be attenuated in insulin resistance." (PMID 23320804, 2013). "Taken together, the higher levels of plasma FGF21 in women with GDM could be a compensatory response to the underlying differences in maternal physiology such as higher insulin resistance at the start of the pregnancy and/or poorer reserve in insulin secretion capacity in GDM subjects." (PMID 23755203, 2013). "Thus, reduced blood glucose concentrations following acarbose treatment may result in (i) markedly lower stimulation of insulin synthesis and insulin secretion and (ii) decreased insulin resistance-induced hyperinsulinemia." (PMID 23642288, 2013).
Insulin resistance (continued). "Therefore, resistin may have an indirect effect on insulin resistance in humans through exacerbating inflammation, which has been shown to disturb insulin sensitivity." (PMID 24455420, 2013). "However, homeostatic model assessment of insulin is a reliable indicator of insulin resistance." (PMID 24058515, 2013). "In the high-dose group, the insulin resistance was seemingly mediated by increasing glucokinase activity and reducing hepatic glucose output for liver glycogen deposition to enhance glucose utilization accompanying improvement in oral glucose and insulin tolerance." (PMID 24371433, 2013). "In addition, it has been postulated that PPARγ may have an effect on lipid metabolism, insulin resistance, and insulin secretion by inducing the transcription of target genes." (PMID 23991018, 2013). "The derived insulin resistance and insulin sensitivity indices,homeostatic modelassessment (HOMA-IR) and quantitativeinsulin sensitivity checkindex (QUICKI), respectively, revealed a worsened insulinresistance and decreased insulin sensitivity in Rap1-deficientfemales." (PMID 23791526, 2013). "This process is also associated with the activation of macrophages, oxidative stress, and inflammation which produce cytokines that have negative effects on insulin sensitivity, induce the secretion of adipokines that cause insulin resistance, and suppress those that promote insulin sensitivity." (PMID 23533299, 2013). "It is now becoming evident that decreased insulin neurotrophic support in the PNS is an integral part of DN and may be a congruent mechanism between type 1 and type 2 diabetic models of DN, as both have reduced insulin signaling either due to insulinopenia or neuronal insulin resistance." (PMID 24252636, 2013). "In addition, previous studies have suggested that muscle activity of lipoprotein lipase (LPL) is related to insulin resistance and that insulin may downregulate the activity of lipoprotein lipase in skeletal muscle." (PMID 24098655, 2013). "In this scenario, the pivotal involvement of the insulin-mediated pathway in determining the ability of DR to induce anti-tumor effects supports the hypothesis that drugs that ameliorate insulin resistance in type 2 diabetes might be beneficial in preventing cancer, even in non-diabetic patients." (PMID 23986086, 2013). "High consumption of red meat may increase insulin resistance, oxidative stress and inflammation, whereas high intake of whole grains may provide protection by improving insulin sensitivity, lowering insulin and glucose levels, and by inhibiting inflammation and oxidative stress." (PMID 22426755, 2013). "Hence, the ability to increase GLP1R protein levels in pancreatic islets during early insulin resistance may be important to facilitate the compensatory increase in β-cell insulin secretion, maintaining normal glucose tolerance." (PMID 23781322, 2013). "However, future studies are also required to explore the long-term effects of resistance exercise training on insulin resistance as well as determining the optimal exercise modality, as the effective therapeutic strategy to reduce insulin resistance in this population." (PMID 24454364, 2013). "The improvement in insulin sensitivity was correlated with the improved cardiorespiratory fitness levels but not with body composition changes, suggesting that fitness level is of importance to reduce or prevent insulin resistance in obese children and adolescents." (PMID 24454364, 2013). "This suggests that acute lack of α2AMPK activation may not directly trigger impaired insulin action, but rather lack of α2AMPK activity over time leads to a muscle phenotype that is more susceptible for insulin resistance." (PMID 23671593, 2013).
Insulin resistance (continued). "This index thus assesses true insulin secretion in relation to insulin sensitivity; it has been called adaptation index and, together with the classic disposition index, provides a comprehensive picture of the mechanism of the beta cell functioning in relation to the prevailing insulin resistance." (PMID 23762879, 2013). "Thus, we suggest that the GLP1 system is upregulated during insulin resistance, through increased responsiveness of islet β-cells to GLP1 and intestinal L-cells to appropriate stimuli, facilitating the compensatory increase in insulin secretion during insulin resistance." (PMID 23781322, 2013). "However, it is notable that, whereas body fat was strongly associated with indicators of insulin resistance (fasting insulin and HOMA IR), no form of dietary fat intake was correlated to these measures." (PMID 24376410, 2013). "It is worthy of note that cross talk between insulin/insulin like growth factor receptor signaling and the Wnt signaling pathway has been established although non-canonical Wnt signaling rather than the canonical pathway is linked to insulin resistance." (PMID 23405249, 2013). "Collectively, these results demonstrated PKCβ deficiency enhances insulin sensitivity with no further improvement by exercise, suggesting exercise-induced improvements in insulin resistance may involve PKCβ-mediated pathways." (PMID 24349059, 2013). "Interestingly, PPARG is one of the few genes that were confirmed to be associated with insulin resistance, Significantly greater insulin sensitivity was reported in not only nondiabetic alanine (Ala) carriers, but also the diabetic patients." (PMID 23997649, 2013). "Adipose insulin resistance is usually due to inflammation associated with obesity and the accumulation of excess lipids, but is typically not detected until it causes the loss of skeletal muscle insulin sensitivity." (PMID 23997935, 2013). "Supporting this hypothesis, a genetic variant near IRS1, that is associated with reduced basal levels of IRS1 protein and decreased insulin induction of IRS1-associated PI-3K activity in human skeletal muscle biopsies, is associated with type 2 diabetes, insulin resistance and hyperinsulinemia." (PMID 23468892, 2013). "The normal insulin sensitivity and glucose tolerance seen here in the twin IUGR lamb may therefore reflect the beginnings of the reversal from insulin sensitivity to insulin resistance occurring during the neonatal catch-up growth they are experiencing at this age." (PMID 23424667, 2013). "Whilst this treatment did not cause changes in basal glucose and insulin concentrations, subtle differential alterations were seen in EtOH-exposed offspring during challenges, with four month old males displaying insulin resistance and females displaying enhanced glucose clearance." (PMID 23533642, 2013). "Besides, unmeasured fetal or placental factors that influence insulin resistance may have a greater impact on antenatal insulin treament." (PMID 23976911, 2013). "Although resveratrol did have positive effects on adiposity and cyclicity in a similar manner to exercise, resveratrol does not seem to be a good candidate for treating insulin resistance associated with PCOS because no improvement in insulin sensitivity was observed in PCOS rats on normal chow." (PMID 23690868, 2013). "In addition, supporting the findings of insulin secretion and islet hypertrophy, the beta cell mass increased in the HF, HF-A, and HF-L groups, and the disorganized histoarchitecture was consistent with the dysfunction of beta cells and insulin resistance." (PMID 23894285, 2013). "Insulin may also be involved in the activation of protein synthesis, but it also difficult to assess the role of insulin in these changes since both the plasma insulin and tissue insulin resistance is greatly increased in this model." (PMID 23527196, 2013).
Insulin resistance (continued). "Therefore, in this previously N(t)RTIs treated HIV population those with some degree of insulin resistance at baseline may gain limb fat to a greater degree because of the improvement in insulin sensitivity." (PMID 24204757, 2013). "It is possible that during insulin resistance, increased IL-6 not only diminishes insulin sensitivity but by suppressing insulin signal transduction also interferes with anti-inflammatory effect of insulin, and might favour inflammation during insulin resistance." (PMID 23805905, 2013). "In addition, one previous study among Pima Indians found that GGT was associated with both hepatic insulin resistance and later declines in hepatic insulin sensitivity in nondiabetic subjects, as well as the development of type 2 diabetes." (PMID 23671610, 2013). "In a state of insulin resistance, insulin-stimulated glucose disposal in skeletal muscle is markedly impaired, which may be associated with impaired insulin signaling, multiple post-receptor intracellular defects, and reduced glucose oxidation and glycogen synthesis." (PMID 23326526, 2013). "However, evodiamine inhibited insulin-stimulated phosphorylation of mTOR and S6K, leading to suppression of IRS1 serine phosphorylation in adipocytes, suggesting evodiamine acts to improve insulin resistance by repressing activation of mTOR-S6K signaling by insulin." (PMID 24391749, 2013). "One study demonstrates that, alteration in the concentration of zinc in obesity may contribute to the development of insulin resistance as zinc improves the solubility of insulin in the beta cells of pancreas and increases the capacity of the receptor for binding this hormone." (PMID 23613929, 2013). "Consequently, much effort has been expended in an attempt to understand the molecular mechanism by which insulin regulates the subcellular trafficking of Glut4 and the possible derangements in this process that may result in insulin resistance." (PMID 23874650, 2013). "However, some studies have evidenced that exercise alone can have a positive impact on insulin resistance risk in obese youth, without changes in body composition, probably exercise-induced improvements in insulin metabolism." (PMID 23443001, 2013). "The mechanisms of insulin resistance include defects in insulin receptors due to genetic defect or insulin receptor antibodies, interference with intracellular insulin action due to the excess of counter-regulatory hormones or inflammatory cytokines, and increased insulin clearance." (PMID 23424687, 2013). "Iron is a potent metal and could convert inactive free radicals to highly active free radicals which could potentially interfere with insulin synthesis and secretion in the pancreas, leading initially to insulin resistance and later to reduced insulin secretion." (PMID 23509453, 2013). "Given the earlier findings that POPs appear to exacerbate insulin resistance, whereas n−3 PUFAs have been demonstrated to attenuate development of diet-induced insulin resistance, we measured fasting levels of glucose and insulin, and performed glucose and insulin tolerance tests." (PMID 23301026, 2013). "Interestingly, adoptive transfer of CD4+ cells especially Th2 CD4+ T cells, which produce IL-4 and IL-13, rescues HFD-induced obesity and insulin resistance in Rag1 deficient mice suggesting that Th2 cytokines such as IL-4 and IL-13 suppress HFD-induced inflammation to improve insulin sensitivity." (PMID 23781214, 2013). "Despite this our data suggests that VDR polymorphisms may contribute to MetSyn component severity such as insulin secretion, insulin resistance and HDL-cholesterol, findings that warrant further examination in larger cohorts with data permitting genome wide association studies to be made." (PMID 23855914, 2013).
Insulin resistance (continued). "As there is evidence for insulin signaling molecules expression in islets itself and because RAS is implicated in the pathogenesis of insulin resistance, it is possible that local RAS expressed in islets may affect GSIS through insulin signaling pathway of β-cell." (PMID 24371439, 2013). "In addition to the association between abdominal adiposity and decreased insulin sensitivity, we found that mean nocturnal SpO2, i.e. nocturnal hypoxia, was inversely correlated with insulin resistance in these non-obese men with obstructive apnea syndrome." (PMID 23951064, 2013). "Moreover, TNF-alpha also has a role in the development of insulin resistance; in fact, it affects insulin sensitivity by changing the phosphorylation of insulin receptor substrate-1 and interferes with the insulin signaling cascade, thereby leading to insulin resistance." (PMID 24259948, 2013). "The ectopic deposition in skeletal muscle of fat as intramyocellular lipid may also play a direct role in the pathogenesis of insulin resistance and metabolic syndrome via lipid metabolite-induced activation of protein PKCɛ with subsequent impairment of insulin signaling." (PMID 23356701, 2013). "In the 1960s, however, the development of the insulin radioimmunoassay led to the finding that plasma insulin levels were often high in T2D, leading many to assume that the pathogenesis could be explained by insulin resistance alone." (PMID 23363033, 2013). "Chronic inflammation within adipose tissue has been implicated in the pathogenesis of peripheral insulin resistance, and levels of fat-derived hormones (specifically the leptin : adiponectin ratio, LAR) have recently been shown to correlate well with clamp measures of whole body insulin sensitivity." (PMID 23737780, 2013). "Changes in behavior, insulin signaling and Alzheimer-associated mRNA expression in the brain were measured in male Wistar rats fed a high fat/high fructose (HF/HFr) diet to induce insulin resistance, with or without CN, for 12 weeks." (PMID 24349472, 2013). "However, fasting mammals exhibit hypoinsulinemia, suggesting that the insulin resistance-like conditions they experience may actually result from reduced pancreatic sensitivity to glucose/capacity to secrete insulin." (PMID 23997935, 2013). "While insulin-induced Thr308 phosphorylation of Akt is down-regulated in E2-transfected Huh7 cell suggesting that HCV E2 protein-induced insulin resistance may occur via a downregulation of Thr308 phosphorylation of Akt, which may serve as a signature molecule in HCV E2-mediated insulin resistance." (PMID 22721429, 2012). "Indeed, while initially there is insulin resistance in type 2 diabetes, as the disease progresses there is also insulin deficiency secondary to the exhaustion of pancreatic beta cells (which have produced large amounts of insulin to compensate for the insulin resistance)." (PMID 22934044, 2012). "In addition, all control subjects have normal weight and insulin sensitivity, and we need samples from control women with obesity or insulin resistance for comparison to further analyze the effect of obesity and insulin resistance on the metabolic changes in PCOS." (PMID 23198915, 2012). "Taken together, accumulating evidence strongly suggests that a single molecule, suppressor of cytokine signaling 3 (SOCS3), may mediate both leptin and insulin resistance due to its ability to inhibit leptin and insulin signaling in both central and peripheral target tissues." (PMID 23115649, 2012). "TRIB3 (a mammalian tribbles homolog, also known as TRIB3/NIPK, gene ID 57761), has been reported by most studies, although not all studies, implicated in the regulation of insulin signal transduction by binding to and inhibiting Akt phosphorylation and to play a role in insulin resistance." (PMID 23245314, 2012).